APOL1 (apolipoprotein L1)
Diseases named in the same sentence as APOL1 in open-access papers (continued):
Sharing a sentence is not in itself a finding about the gene and the disease.
melanoma (1 paper, 2021). A malignant, usually aggressive tumor composed of atypical, neoplastic melanocytes. "The results confirmed that APOL1 have higher expression in GSE46517 while ATG16L2, DAPK2, ATG9B and EGFR have lower expression in GSE15605 for primary melanoma compared with normal skin." (PMID 34809598, 2021). "ApoL1, a BH3-only protein, is the major apoprotein of high-density lipoprotein and has never been studied in melanoma, but APOL1 is overexpressed in a variety of cancer cell types to induce autophagy and autophagy-associated cell death." (PMID 34809598, 2021).
meningioma (1 paper, 2020). A generally slow growing tumor attached to the dura mater. "The human apolipoprotein L1 (APOL1) was uniquely identified in male grade I meningiomas (Supplementaty file 3)." (PMID 32587372, 2020).
parasite (1 paper, 2024). "APOL1 expression is strongly increased under inflammatory conditions linked to viral or parasite infection, and APOL evolution in primates suggests a role in resistance to pathogens." (PMID 39451256, 2024).
parvovirus infection (1 paper, 2016). "This is the first published case report of CG in the setting of acute parvovirus infection in a patient with two APOL1 risk allelles, and parvoviral proteins identified in renal epithelium on kidney biopsy." (PMID 27600725, 2016).
periodontitis (1 paper, 2019). An acute or chronic inflammatory process that affects the tissues that surround and support the teeth. "Therefore, we speculate that due to changed concentrations and activities of major HDL remodelling factors, probably generating less apoL-1-associated HDL particles during periodontitis, apoL-1 is redistributed to LDL/VLDL particles." (PMID 30842338, 2019). "In addition, apoL-1 correlated with BOP, apoB/apoA-I ratio and apoC-II further suggesting an involvement in the inflammation in periodontitis." (PMID 30842338, 2019).
placental insufficiency (1 paper, 2025). Failure of the placenta to deliver an adequate supply of nutrients and oxygen to the fetus. "The function of APOL1 in the placenta and the mechanism by which APOL1 risk variants lead to placental insufficiency and pregnancy complications are unknown." (PMID 40940784, 2025).
pneumonia (1 paper, 2023). An acute, acute and chronic, or chronic inflammation focally or diffusely affecting the lung parenchyma, caused by an infection in one or both of the lungs (by bacteria, viruses, fungi, or mycoplasma.). "Finally, P17 (critical pneumonia) was found to be homozygous for a p.E941K variant in APOL1." (PMID 36880831, 2023).
sarcoidosis (1 paper, 2022). Sarcoidosis is a multisystemic disorder of unknown cause characterized by the formation of immune granulomas in involved organs. "Furthermore, non-synonymous SNPs in LILRB2, GZMB, APOL1, CNN2, SWAP70, and CSF1R were shown in over 50% of sarcoidosis patients." (PMID 35860586, 2022).
sarcoma (1 paper, 2021). A usually aggressive malignant neoplasm of the soft tissue or bone. "In addition to sarcomas, high expression of APOL1 can induce autophagy and autophagy-related cell death, which may be the key to maintaining cell homeostasis in the kidney." (PMID 33435917, 2021).
thyroid autoimmunity (1 paper, 2025). "Genetic factors such as APOL1 risk variants, which are prevalent in individuals of African ancestry and linked to renal manifestations of SLE, may reflect broader immune dysregulation with potential relevance to thyroid autoimmunity." (PMID 41234630, 2025).
thyroid tumor (1 paper, 2025). A benign or malignant neoplasm affecting the thyroid gland. "These aspects will be prioritized in our future research to deepen our understanding of APOL1’s role in thyroid tumor immunobiology." (PMID 41378287, 2025).
transthyretin amyloidosis (1 paper, 2020). "Pathogenic ClinVar two-star variants and APOL1 renal risk variants were identified across all these groups, including TTR rs76992529 associated with amyloidogenic transthyretin amyloidosis, otherwise known as autosomal dominant familial transthyretin amyloidosis (FTA)." (PMID 31797629, 2020).
vitiligo (1 paper, 2024). Generalized well circumscribed patches of leukoderma that are generally distributed over symmetric body locations and is due to autoimmune destruction of melanocytes. "APOL1 has shown to be upregulated in response to inflammation through the Janus kinase signal transducer and activator of transcription (JAK-STAT) pathway, a pathway also involved in the vitiligo pathogenesis." (PMID 38715599, 2024). "This analysis showed peroxiredoxin-6 (PRDX6) and apolipoprotein L1 (APOL1) to be downregulated in patients with progressive and stable vitiligo compared to healthy controls, with in both cases the protein being more downregulated in progressive vitiligo compared to stable vitiligo." (PMID 38715599, 2024).
kidney disease (298 papers, 2011 to 2026). "The high risk APOL1 G1/G2 variants contribute to the development of kidney disease in individuals of African ancestry, including those with SCA." (PMID 41870384, 2026). "The significance of context-dependent pathogenic processes is highlighted by the poor penetrance and remarkable phenotypic variety of APOL1-associated kidney disease, despite its substantial impact." (PMID 41898722, 2026). "Twenty-four participants met CARE Registry criteria, and seven enrolled in the Janus kinase-Signal Transducers and Activators of Transcription Inhibition to Reduce APOL1-Associated Kidney Disease trial." (PMID 41774497, 2026). "APOL1 was previously reported to be associated with kidney diseases in individuals of African ancestry." (PMID 41541644, 2026). "The study identifiedthat APOL1 kidney risk variants were associated with higher rates ofend-stage kidney disease and progression of chronic kidney disease in blackpatients relative to white patients, regardless of diabetes status." (PMID 41511474, 2026). "The discovery of apolipoprotein L1 (APOL1) risk polymorphisms has significantly changed our knowledge of kidney disease susceptibility and development in African American populations." (PMID 41898722, 2026). "Exonic variants in Apolipoprotein-L1 (G1 and G2) are linked to increased risk of kidney disease as well as kidney transplant rejection." (PMID 42262888, 2026). "The APOL1 gene variants G1 and G2 are associated with an increased risk of APOL1-mediated kidney disease." (PMID 41807048, 2026). "Development of APOL1-mediated kidney disease is a notable risk in transplant recipients receiving kidneys from donors with APOL1 high RRVs." (PMID 41010023, 2025). "In the United States, an estimated 13% of African American people carry two APOL1 RRVs, elevating their susceptibility to kidney disease." (PMID 41010023, 2025). "Our group and others showed that a missense variant in APOL1, rs73885316 (p.N264K, “M1”), is remarkably protective against APOL1 kidney disease when co-inherited with the G2 risk allele." (PMID 39658338, 2025). "Another important, unresolved question is the mechanism by which the two APOL1 risk variants cause kidney disease." (PMID 39927257, 2025). "In United States, six million individuals with sub-Saharan ancestry carry two APOL1 high-risk variants, which increase the risk for kidney diseases." (PMID 40459058, 2025). "APOL1 coding variants, termed G1 and G2, are established genetic risk factors for kidney disease, in individuals of African ancestry." (PMID 40236664, 2025). "In recent years, APOL1-mediated kidney disease (such as FSGS in carriers of two APOL1 risk alleles) has become a focus of precision medicine research." (PMID 40563449, 2025). "Despite prior evidence linking APOL1 G1/G2 variants to kidney disease and their strong pQTL effects on plasma APOL1 observed in our study, we did not detect a significant association between these variants and ESRD risk in the UK Biobank." (PMID 39975113, 2025). "It is thought that high-risk variants cause APOL1-mediated kidney disease in a way that is very similar to how it causes cytotoxicity in laboratory animals." (PMID 40027896, 2025). "APOL1 gene variants are associated with an increased risk of kidney disease, particularly in individuals of African origin." (PMID 41225540, 2025). "Numerous studies have shown that APOL1 G1 and G2 cause kidney disease by what appears to be a recessive gain-of-function mechanism." (PMID 39927257, 2025). "Initial studies described genetic variants of the MYH9 gene, but subsequent studies revealed a high linkage disequilibrium of MYH9 with APOL1, with the latter having a higher association with kidney disease." (PMID 39857298, 2025). "APOL1 gene variants are significant risk factors for various forms of kidney dysfunction, and GSDMD has been identified as a key regulator in APOL1-associated kidney diseases." (PMID 39994107, 2025).
kidney disease (continued). "APOL1 risk variants are linked to accelerated fibrosis in the kidneys, contributing to the progression of kidney disease, which has been shown in human cellular and mouse models." (PMID 41225540, 2025). "Much progress has been achieved in unravelling molecular mechanisms, interactions and pathways involved in APOL1 causation of gain of cell injury, and in turn its most prominent ostensible clinical manifestation—kidney disease risk." (PMID 40643530, 2025). "The G1 and G2 variants of the gene encoding Apolipoprotein L1 (APOL1) increase risk for kidney disease and cardiometabolic traits." (PMID 40501951, 2025). "The kidney disease risk variants, APOL1-derived G1 and G2, rose to high frequency in Western and Central Africa in response to selective pressure from the emergence of Trypanosoma species with extended virulence (Trypanosoma brucei gambiense and rhodesiense)." (PMID 39927257, 2025). "Given the recipient’s young age at onset of kidney disease, race and for prognostication after kidney transplantation, genetic testing was performed, revealing high-risk APOL1 genotype (homozygote G1)." (PMID 40821938, 2025). "Individuals with 2 copies of the APOL1 G1 or APOL1 G2 risk variants (RV) face increased risk for kidney disease and possibly cardiometabolic traits compared to those with at least one copy of the non-risk allele (G0)." (PMID 40501951, 2025). "This toxicity leads to podocyte injury and the development of CG, underscoring that individuals with the APOL1 high‐risk genotype are at increased risk for an aggressive form of kidney disease when infected with specific viruses." (PMID 41397399, 2025). "APOL1 risk variants, unique to populations with sub-Saharan ancestry, are associated with increased risk for kidney diseases." (PMID 40459058, 2025). "Baricitinib acts as an effective inhibitor of this signaling cascade, highlighting its strong potential as a therapeutic option for APOL1-associated kidney diseases." (PMID 41225540, 2025). "Novel mechanisms, such as microbiome dysbiosis and apolipoprotein L1 gene mutation, have improved our understanding of kidney disease mechanisms." (PMID 40027896, 2025). "The increased risk for renal diseases mediated by the APOL1 RRVs follows a recessive inheritance pattern, meaning that two risk alleles (G1/G1, G2/G2, or G1/G2) are required to confer increased susceptibility to kidney disease." (PMID 40643483, 2025). "Studying high-risk populations has yielded one of the most important advances in kidney disease—the identification of APOL1 high risk genotypes, for which promising therapies are now under development." (PMID 39636884, 2024). "Few participants had both a monogenic kidney disorder and a high-risk APOL1 genotype, with the majority being in type 4 collagen genes (5 CureGN participants, 1 Columbia-GN participant, and 6 Columbia-CKD participants)." (PMID 39225089, 2024). "APOL1 is expressed in several kidney cell types, but the mechanisms by which the high-risk variants cause kidney disease are not yet well understood." (PMID 38791464, 2024). "Transcriptomic investigations across ethnicities, for example, have revealed diversity in gene expression related with disease vulnerability, such as APOL1-associated kidney disease in African populations." (PMID 39728069, 2024). "Our initial analysis identified 3 significant variants other than APOL1 G1/G2 with significant kidney disease associations." (PMID 39163132, 2024). "Our approach identified multiple AFR-specific protein-altering variants in the APOL gene family implicated in kidney disease risk, including a stop-gain variant in APOL3 that increases the risk of CKD primarily in persons carrying 1 APOL1 G1/G2 risk allele." (PMID 39163132, 2024). "Since the transgenic expression of the APOL1 G1 and G2 variants in mice can induce kidney disease, I propose that mAPOL8 is the mouse APOL family member inactivated by the APOL1 variants." (PMID 38478101, 2024).
kidney disease (continued). "Since 2016, our department has been screening for high-risk APOL1 variants in all patients who originate from sub-Saharan Africa and the French West Indies and who are being investigated for kidney disease." (PMID 38899219, 2024). "Genetic analysis of 5,727 patients with kidney disease from 3 diverse cohorts identified 371 patients (6.5%) with monogenic kidney disorders, 318 (5.5%) with high-risk APOL1 genotypes, and 100 (5.2%) in CureGN with ACMG SFs." (PMID 39225089, 2024). "In USA, six million individuals with Sub-Saharan ancestry carry two APOL1 high-risk variants, which increase the risk for kidney diseases." (PMID 39803526, 2024). "The mechanism by which G1 and G2 — collectively called APOL1 renal risk variants (RRVs) — cause kidney disease is poorly understood." (PMID 38227370, 2024). "Monogenic kidney disorders were identified in 371 patients (6.5%), high-risk APOL1 genotypes in 318 (5.5%), and ACMG SFs in 100 (5.2%)." (PMID 39225089, 2024). "Recurrence of kidney disease is a leading cause of transplant loss, and APOL1 testing would help guide counseling of patients about their risk of kidney disease recurrence post-transplantation." (PMID 39271961, 2024). "Homozygous Apolipoprotein L1 (APOL1) variants G1 and G2 cause APOL1-mediated kidney disease, purportedly acting as surface cation channels in podocytes." (PMID 38355600, 2024). "Genomics enables the discovery of hereditary kidney disease subgroups with discrete molecular pathways, such as APOL1 mutations, which guide transplant decisions, while medications like VX-407 target specific polycystic kidney disease variants." (PMID 39728069, 2024). "The multiplexed CRISPR assay reported detects two variants in the APOL1 gene relevant for kidney disease and transplantation." (PMID 39271961, 2024). "The discovery of the apolipoprotein L1 gene (APOL-1) as a kidney disease risk gene revealed a genetic contribution to the racial and ethnic disparity observed in CKD." (PMID 40125376, 2024). "Two coding variants of apolipoprotein L1 (APOL1), called G1 and G2, explain much of the excess risk of kidney disease in African Americans." (PMID 38227370, 2024). "These APOL1 risk variants (RVs) are linked to a spectrum of kidney diseases, including HIV-associated nephropathy, focal segmental glomerulosclerosis, sickle cell nephropathy, and lupus nephritis." (PMID 38542298, 2024). "Apolipoprotein L1 (APOL1) coding variants, termed G1 and G2, are established genetic risk factors for a growing spectrum of diseases, including kidney disease, in individuals of African ancestry." (PMID 38714935, 2024). "Currently, ethnicity is employed as a rudimentary indicator of APOL1-mediated kidney disease risk in clinical practice." (PMID 39271961, 2024). "We applied this assay to identify genetic variants in the APOL1 gene prevalent among African Americans, which are associated with an 8–30-fold increase in the risk of developing kidney disease." (PMID 39271961, 2024). "Novel therapies tested for APOL1-associated kidney disease include small molecule compounds that bind to the APOL1 protein to inhibit APOL1 channel function." (PMID 38714935, 2024). "Specifically, Gia states: “Genetic testing for APOL1, along with all the other donor tests, helps the transplant team better understand your personal risk of getting kidney disease after donating." (PMID 38349598, 2024). "The inclusion of various populations in multi-omics research improves the discovery of novel molecular markers and genetic connections, which are especially relevant for discovering risk factors for APOL1-associated kidney disease." (PMID 39728069, 2024). "The APOL1 risk variants cause large increases in susceptibility to multiple different types of kidney disease including hypertension-associated ESRD, FSGS and HIV-associated nephropathy." (PMID 39056771, 2024).